INS (insulin)
Diseases named in the same sentence as INS in open-access papers (continued):
Sharing a sentence is not in itself a finding about the gene and the disease.
diabetes (continued). "Diabetes is not considered a contraindication for the administration of corticosteroids for fetal lung maturation, but this procedure should be precisely planned with increased dosages of insulin." (PMID 26983627, 2016). "In diabetes, which is characterised by an absence of insulin or increased peripheral insulin resistance (or both), a reduction in insulin receptor (IR) to IRS to PI3K to Akt signalling leads to acceleration of atherosclerosis because of the loss of anti-atherogenic insulin signalling." (PMID 27514532, 2016). "The different methods and populations assessed in the studies do not allow us to state whether early insulin therapy should or should not be carried out in patients with cystic fibrosis prior to the diagnosis of diabetes." (PMID 26994743, 2016). "Moreover, elevated levels of 2-hour glucose and insulin are indicators of impaired glucose tolerance and insulin resistance in PCOS patients and are thus used to predict patients’ risks for metabolic syndrome and diabetes." (PMID 27124836, 2016). "Diabetes mellitus is a metabolic disorder characterised by derangement in carbohydrate, protein, and fat metabolisms resulting from impairment in glucose homeostasis, lack of insulin secretion, and development of macro- and microvascular dysfunctions." (PMID 27208974, 2016). "As insulin can modify inflammatory and procoagulant responses independently of glucose levels we sought to compare the host response in insulin-treated versus non-insulin-treated patients with diabetes mellitus." (PMID 27495247, 2016). "As a whole, this study describes the mechanisms involved in the insulin sensitizing effect of APE, which could be considered a promising ingredient for inclusion in nutritional products focused on the management of chronic diseases such as diabetes." (PMID 27141227, 2016). "This difference may represent either a less severe phenotype, as our participants did not have diabetes, or the historical use of non‐specific insulin radioimmunoassays that were prone to cross‐reactivity with insulin‐like molecules." (PMID 26606753, 2016). "Due to the dose of STZ, non-ketonuric diabetes mellitus, where the animals can be maintained without insulin treatment for more than 100 days, could be separated from animals with a severe form of diabetes, suffering from diabetic ketoacidosis." (PMID 27253523, 2016). "Insulin sensitivity in clamp studies was independently associated with serum bicarbonate and apolipoprotein A1: apolipoprotein B ratio in a sample of CKD patients without diabetes." (PMID 27716263, 2016). "The importance of insulin secretagogues as a remedy for combating diabetes was highlighted in the Kyoto declaration of 2013, where nonobese type 2 diabetic patients mostly of Asian origin were observed to possess defects in insulin secretion rather than insulin resistance." (PMID 27594892, 2016). "However, administration of exogenous insulin fails to mimic the physiological activity of the islet, therefore diabetes often progresses with the development of serious complications such as kidney failure, retinopathy and vascular disease." (PMID 27400873, 2016). "That Akt can accomplish its enzymatic function without undergoing Ser473 phosphorylation is demonstrated by the finding that muscle-specific rictor KO mice simply present with a moderately decreased insulin-stimulated glucose uptake and glucose intolerance, but not diabetes." (PMID 27149630, 2016). "Therefore, our obese canine model represents an insulin resistant phenotype, but not frank diabetes." (PMID 27802272, 2016). "Even though we adjusted models for multiple confounding factors we were unable to adjust models for other important factors for which measures were not available, including glycaemic control, plasma insulin level, type of diabetes, duration of diabetes, and level of renal function." (PMID 27195294, 2016).
diabetes (continued). "According to data from the Wisconsin Epidemiologic Study of Diabetic Retinopathy (WESDR), after 15 years of known diabetes, the prevalence of diabetic macular edema is approximately 25% and 14% in patients with type 2 DM treated with and without insulin, respectively." (PMID 27200379, 2016). "Glutamic acid decarboxylase autoantibodies (GADAb) differentiate slowly progressive insulin-dependent (type 1) diabetes mellitus (SPIDDM) from phenotypic type 2 diabetes, but many GADAb-positive patients with diabetes do not progress to insulin-requiring diabetes." (PMID 27177031, 2016). "Sessions of high blood sugar can exert toxic effects, glucotoxicity, on the beta cells of the pancreas and lead to the “early stage” diabetes, ET2D, when there is insufficient production of insulin due to partial beta cell destruction, and FBS test may show slightly above normal." (PMID 26877773, 2016). "In alignment with other published studies our research didn’t find association between cholesterol levels, insulin levels and HOMA-IR with antiviral response this may be probably explained by the absence of diabetes among our patients." (PMID 26911666, 2016). "Although the pathological effects of MG in diabetes and diabetic complications are known, there is little evidence showing whether MG has an impact on insulin secretion by β-cells." (PMID 26779540, 2016). "Thus, our study has revealed that Inpp5f provides as a negative feedback regulator of insulin signaling and downregulation of Inpp5f in diabetes is cardioprotective." (PMID 26908121, 2016). "When insulin is given to experimentally induce hypoglycemia in people without diabetes, glucose levels at or below ~3.8 mmol/L will induce a glucagon response, the secretion of which by pancreatic alpha-cells is probably controlled by the neighboring beta-cells." (PMID 26521082, 2016). "In type 1 diabetes mellitus (T1DM), defective insulin secretion occurs due to dysfunctional pancreatic β-cells or a decrease in β-cell mass over time, whereas in type 2 diabetes mellitus (T2DM), insulin-stimulated glucose uptake in hepatic and adipose tissues is reduced due to insulin resistance." (PMID 27721914, 2016). "A conciliatory view of most conflicting clinical and experimental data is that CETP per se is not relevant to glucose homeostasis/insulin sensitivity, but actually the HDL-cholesterol levels and perhaps the HDL functionality is important to regulate glucose metabolism and modulate diabetes risk." (PMID 26758205, 2016). "Although the patients with complications had higher level of HbA1c and insulin, we could not find any correlation between hyperglycemia markers and bone markers after adjustment for age, sex, obesity and diabetes complications." (PMID 27826545, 2016). "Thus, C-peptide has the ability to measure endogenous insulin secretion in patients with diabetes irrespective of insulin therapy." (PMID 27196896, 2016). "Mice with 7,8-DHF treatment also exhibit improved blood insulin concentration, lower blood glucose level and increased insulin sensitivity in tissues such as liver, fat and muscles, suggesting 7,8-DHF is effective in alleviating the obesity-induced diabetes as well." (PMID 26740873, 2016). "Finally, we did not measure other diabetes related factors such as fasting glucose, 2-hour postload glucose, fasting insulin and insulin resistance." (PMID 27629481, 2016). "Owners are important collaborators in feline diabetes care and, with intensive home monitoring, more frequent insulin treatment may lead to remission without hypoglycemia." (PMID 27766967, 2016). "However, Henry Rusinek and his colleagues found that no hypoperfusion exists in diabetes group, in contrast to hypoperfusion in insulin resistant but not diabetes group." (PMID 27552827, 2016). "No further insulin was needed, and he did not require any diabetes medications on discharge." (PMID 26788532, 2016).
diabetes (continued). "The fact that diabetic patients have too little insulin, as well as uncontrolled levels of glucagon, has led to the hypothesis that diabetes is triggered by inappropriate levels of both hormones, not just insulin alone." (PMID 27190125, 2016). "Furthermore, estrogen replacement therapy did not change HbA1c and insulin area under the OGTT curve in patients with diabetes or change glucose tolerance or glucose uptake by the hyperinsulinemiceuglycemic clamp in healthy postmenopausal women." (PMID 27275336, 2016). "Consequently, recent studies among hyperglycemic individuals with no prior diagnosis of diabetes mellitus found to improve insulin sensitivity and other important metabolic controls." (PMID 27733151, 2016). "Individuals with type 2 diabetes mellitus (T2DM) generally lose their ability to secrete insulin in response to carbohydrates; however, they are able to retain, or potentially even increase their ability to secrete insulin in response to protein and amino acid ingestion." (PMID 27455320, 2016). "In obesity and diabetes, non-esterified fatty acids which are a component of the high fat diet, are important contributors to oxidative and ER stress in pancreatic β-cells, which are insulin-producing secretory cells." (PMID 27350069, 2016). "This peptide may provide a template to develop anti-diabetic drugs that function independent of proximal insulin signaling, which is often impaired in diabetes." (PMID 27537838, 2016). "IGF-1 is also strongly linked to glucose-insulin pathways, however, the link to diabetes is not altogether easy, as both high and low levels of IGF-1 have been shown to correlate with subsequent onset of diabetes." (PMID 26577692, 2015). "In addition, plasma fasting insulin levels and HOMA-IR values significantly increased in a stepwise fashion from control subjects to patients with NAFLD alone to patients with NAFLD and incident diabetes." (PMID 25961500, 2015). "In addition, the sole prescription of antidiabetic drugs or insulin without a connection to a diabetes specific WHO-ICD-10 code over the whole calendar year was evident in 0.1 % of all insured persons only." (PMID 26334523, 2015). "The routine injection of insulin before meals has substantially improved the lives of people who suffer from diabetes by controlling their hyperglycemia, but this does not address the other aspects of diabetes." (PMID 26230945, 2015). "Due to the positive correlation between Zn and insulin concentrations as well as HOMA-IR in the examined participants without diabetes, lower Zn levels may relate to disturbance of carbohydrate metabolism." (PMID 25867198, 2015). "We also demonstrated that modest weight reduction of about 7% over 6-month period through caloric reduction and increased physical activity improves insulin sensitivity, endothelial function, and several markers of inflammation and coagulation in obese patients with and without diabetes." (PMID 26114120, 2015). "The total number of bolus insulin units taken by patients with type 1 and type 2 diabetes mellitus did not change during the study (20.3 ± 6.5 units and 19.9 ± 5.7 units at baseline to 19.4 ± 7.1 units and 20.1 ± 5.5 units at week 12, 19.0 ± 7.3 units and 20.0 ± 5.6 units at week 24, respectively)." (PMID 26819737, 2015). "However, in our patient the diabetes were being controlled with the current insulin treatment, and also he has no complaints about his muscles." (PMID 25945273, 2015). "Interestingly, the ability of the GM-CSF only hydrogel/MP formulation to prevent diabetes was no better than the no treatment control, highlighting the importance of the CpG and insulin MP components in the formulation." (PMID 26279095, 2015). "However, complete insulin independency did not occur in their study, but safety and effectiveness of ADSCs-based cell therapy in diabetes have been shown." (PMID 26576437, 2015). "It is known that the absence of insulin can induce diabetes." (PMID 25585621, 2015).
diabetes (continued). "The major findings of our analysis are that for both Asian and non-Asian obese T2DM patients, older age, long history of diabetes, insulin use, and poor glycemic control can be assumed to be negative predictors for failure of diabetes remission in the postoperative course." (PMID 25103403, 2015). "INS 30 significantly decreased in people with diabetes than those without diabetes." (PMID 25785633, 2015). "Further adjusting for duration of diabetes and insulin dose did not change the results." (PMID 26325204, 2015). "The diabetes-supportive effect of CD44 expression on β cells was assessed by the TUNEL assay and further strengthened by functional assays exhibiting increased nitric oxide release, reduced insulin secretion after glucose stimulation and decreased insulin content in β cells." (PMID 26624007, 2015). "Here, we analyzed global metabolomic and lipidomic profiles of obese subjects with diabetes at pre-, 4 and 42 days after RYGB, and investigated which metabolites and lipid species correlated with insulin levels and could thus potentially contribute to metabolic improvements." (PMID 25946120, 2015). "Based on these findings, we postulate that glucotoxicity might be important for the progression of DN, but insulin resistance might play a major role in the development of CAA regardless of diabetes type." (PMID 25975731, 2015). "We aimed to establish whether the insulin sensitising drug metformin improves maternal and fetal outcomes in obese pregnant women without diabetes." (PMID 26165398, 2015). "Diabetes implications: The SCALE-Maintenance trial looked at the influence of liraglutide 3.0 mg throughout a 56-week intervention, and as expected, liraglutide users had significantly improved FBG, fasting insulin and HbA1c measurements when compared against placebo participants [51••]." (PMID 25894803, 2015). "Because most patients requiring insulin therapy had a longer known T2DM duration and greater preoperative fasting glucose and HbA1c levels than those not requiring insulin, insulin treatment may impact the severity of diabetes to some degree." (PMID 25103403, 2015). "The obese groups (NGT and IGT+T2D) were similarly insulin resistant but only the diabetics had β-cell failure, which might not relate with oWAT fibrosis." (PMID 26258766, 2015). "Type 2 diabetes mellitus (T2DM) is a complex and chronic disease in which the body fails to respond to the increased level of glucose due to attenuated insulin-stimulated glucose uptake with a normal amount of insulin (insulin resistance) and/or impaired insulin secretion from pancreatic β cells." (PMID 27417763, 2015). "Diabetes is characterized by insufficient secretion rate of insulin or lack of insulin activity." (PMID 27275254, 2015). "However, the requirements of frequent insulin injections and troublesome blood glucose monitoring have been criticized, as well as the lack of cure for diabetes." (PMID 26294917, 2015). "On average, diabetes patients reported monthly costs of Tshs 5,000 (USD 3.2) for consultation and laboratory tests, and of Tshs 4,600 – Tsh 52,000 (USD 2.9 – 33.7) for medicines, depending on whether they were using oral hypoglycemic medications or insulin." (PMID 25890162, 2015). "Respondent demographics show that 6 % of Austrian respondents with T1DM were receiving basal-only insulin, however this formulation should only be used in patients with T2DM, and therefore we presume that most of these respondents incorrectly reported their diabetes type as T1DM." (PMID 25421366, 2015). "This could suggest a preserved ability by which exercise downregulates blood glucose, in NOD mice, when the immune attack has not led yet to frank diabetes, that is, by insulin-stimulated glucose uptake in the skeletal muscle." (PMID 26347378, 2015).
diabetes (continued). "However, we recently reported for this cohort that over 98% of diabetes-diagnosed cases were not prescribed insulin during the first year after diabetes diagnosis, thereby supporting type 2 predominance." (PMID 26305680, 2015). "Furthermore, some diseases and medication were rarely reported by our participants, such as diabetes and insulin or cancer and cytostatic drugs (data not shown)." (PMID 25745506, 2015). "Generic (Short-Form 36 Health Survey - SF-36) and specific (Problem Areas in Diabetes - PAID) HRQoL questionnaires, Beck Depression Inventory (BDI), clinical, laboratorial and socio-demographic data were recorded at baseline and after 6 months of insulin therapy." (PMID 26110026, 2015). "Insulin use rather than diabetes may be the marker of adverse prognosis in patients with systolic HF." (PMID 25880202, 2015). "In contrast, B6 mice had no impairment in insulin sensitivity but developed diabetes." (PMID 25946019, 2015). "The majority of trials did not explicitly provide information on how diabetes was defined with the exception of four trials, in which T2D was defined as fasting plasma glucose ≥7 mmol/L or the use of oral glucose-lowering agents or insulin." (PMID 26633472, 2015). "In this way, it could be of great importance to include melatonin as a complement in insulin treatment of diabetes, given that disruption of the BT rhythm, and probably other rhythms in the organism are not completely reverted by insulin alone." (PMID 25960780, 2015). "The study of endogenous insulin secretion may provide relevant insight into the comparison of the natural history of adult onset latent autoimmune diabetes (LADA) with types 1 and 2 diabetes mellitus." (PMID 25572256, 2015). "A study by Currie and colleagues showed that mortality increased in elderly breast cancer patients with diabetes, and metformin treatment improved survival rates in comparison with other diabetic treatments (sulfonylureas and insulin) and compared to a nondiabetic patient cohort." (PMID 25866793, 2015). "However, clamp studies performed in relatively small number of obese subjects (some of them with diabetes) do not confirm that insulin acutely influenced fibrinolysis." (PMID 26089884, 2015). "Taken together, the 3wHF diet, with continuous weigh gain even through the final week of the diet and modestly, but non-significantly, increased insulin and myostatin levels, establishes a model to test the effects of rapid weight gain in the absence of overt diabetes." (PMID 26539241, 2015). "The rise in insulin secretion in relation to insulin resistance, as expressed by the DIo, in the majority of the group at follow-up explains their lack of development of diabetes." (PMID 26251665, 2015). "However, others admit that insulin alone is insufficient to reverse all the negative impact of diabetes on bone healing, with impaired bone implant integration in both animal models and patients." (PMID 26783411, 2015). "CRT had a beneficial effect on reverse remodeling in all patient groups (without diabetes, with noninsulin-treated diabetes, with insulin-treated diabetes), with a slight but not statistically significant increased improvement in ejection fraction in nondiabetic patients." (PMID 25880202, 2015). "Therefore, preoperative assessment of insulin secretion capacity could be proven useful to grade the stage and severity of T2DM and to predict the diabetes status after RYGB surgery." (PMID 25103403, 2015). "However, it is disconcerting that almost 40–60 % of drivers with insulin-treated diabetes reported that they never test blood glucose before driving, or test only if they feel hypoglycemic." (PMID 28702227, 2015). "While type 1 diabetes mellitus (T1DM) is characterized by pancreatic β-cell destruction usually leading to absolute insulin deficiency, type 2 diabetes mellitus (T2DM) is accompanied by hyperglycemia in the context of insulin resistance and relative lack of insulin." (PMID 25742620, 2015).